IL22RA1 (interleukin 22 receptor subunit alpha 1)
Diseases named in the same sentence as IL22RA1 in open-access papers (continued):
Sharing a sentence is not in itself a finding about the gene and the disease.
chronic graft versus host disease (1 paper, 2023). Chronic graft versus host disease (GVHD) is a complication that can occur after a stem cell or bone marrow transplant in which the newly transplanted donor cells attack the transplant recipient's body. "Targeting AHR or IL-22RA1 had a significant impact on the pathogenesis of murine chronic graft-versus-host disease (cGVHD), an autoimmune-like complication following allo-HCT13." (PMID 37938575, 2023). "Furthermore, targeting AHR or IL-22RA1 has significant impacts on severity of murine chronic graft-versus-host disease (cGVHD), which is an autoimmune-like complication following allogeneic hematopoietic cell transplantation." (PMID 37938575, 2023).
chronic rhinosinusitis (1 paper, 2021). Chronic form of sinusitis. "In an attempt to identify possible genetic mechanisms that trigger chronic rhinosinusitis, we compared the polymorphisms of the IL22RA1 gene in Brazilian CRS samples and in a control group, without CRS." (PMID 31879195, 2021). "Therefore, the present study aimed to identify variants associated with the IL22RA1 gene in Brazilian patients diagnosed with chronic rhinosinusitis and in individuals without this diagnosis." (PMID 31879195, 2021). "Peripheral blood samples were collected from 70 chronic rhinosinusitis with polyps patients, 14 chronic rhinosinusitis without polyps patients and 68 subjects without chronic rhinosinusitis, followed by DNA extraction and IL22RA1 gene sequence analysis." (PMID 31879195, 2021).
Fanconi anemia (1 paper, 2022). Fanconi anemia (FA) is a hereditary DNA repair disorder characterized by progressive pancytopenia with bone marrow failure, variable congenital malformations and predisposition to develop hematological or solid tumors. "IL22RA1 mutation in uterine cancer upregulated genes in the fanconi anemia pathway and homologous recombination which were involved in DNA damage and repair." (PMID 35874683, 2022).
Impaired glucose tolerance (1 paper, 2024). An abnormal resistance to glucose, i.e., a reduction in the ability to maintain glucose levels in the blood stream within normal limits following oral or intravenous administration of glucose. "IL-22RA1 expression in human islets is increased in T2D and impaired glucose tolerance." (PMID 38811550, 2024).
malaria (1 paper, 2016). Malaria is a serious and sometimes fatal disease caused by a parasite that commonly infects a certain type of mosquito which feeds on humans. "However, further investigations are needed to elucidate that IL-22 directly acts on hematopoietic cells expressing the IL-22Rα1 chain during malaria." (PMID 27311945, 2016).
melanoma (1 paper, 2022). A malignant, usually aggressive tumor composed of atypical, neoplastic melanocytes. "In melanoma, a total of 14 genes were upregulated, whereas 77 genes were downregulated when comparing IL22RA1 mutated and wild-type patient cohorts." (PMID 35874683, 2022). "In melanoma, mutation of IL22RA1 can upregulate the HIF signaling pathway but downregulate metabolic pathways." (PMID 35874683, 2022). "IL22RA1 mutation was observed more in uterine cancer and melanoma compared with the other cancer types." (PMID 35874683, 2022). "IL22RA1 mutation in uterine cancer and melanoma induced overexpression of genes that are favorable in tumor progression." (PMID 35874683, 2022). "In melanoma, IL22RA1 mutation upregulated the expression of genes involved in the hypoxia-inducible factor-1alpha (HIF-1α) signaling pathway, whereas the metabolic pathways including biosynthesis of unsaturated fatty acids and butanoate metabolism were downregulated." (PMID 35874683, 2022).
myositis (1 paper, 2025). "Markers of type 3 inflammation were even less commonly overexpressed among the myositis groups, with exceptions being IL22RA1 in DM and CCL20 in Jo1." (PMID 40034760, 2025).
non-small cell lung carcinoma (1 paper, 2021). A group of at least three distinct histological types of lung cancer, including non-small cell squamous cell carcinoma, adenocarcinoma, and large cell carcinoma. "Previous study showed increased serum levels of IL-22 in patients with non-small cell lung carcinoma and IL-22Ra1 expression up-regulated in tumor cells." (PMID 34941188, 2021).
uterine cancer (1 paper, 2022). Primary or metastatic malignant neoplasm involving the uterine corpus and/or the cervix. "Pan-cancer analysis shows that IL22RA1 is highly expressed in 11 types of tumors including uterine cancer." (PMID 35874683, 2022). "IL22RA1 mutants had upregulated DNA damage/repair genes in uterine cancer, whereas downregulated genes in the FoxO signaling pathway." (PMID 35874683, 2022). "The protein level of IL22RA1 was increased in uterine cancer compared with normal control tissues from dogs (p < 0.01)." (PMID 35874683, 2022). "Consistently, we identified that the expression of IL22RA1 in uterine cancer was increased significantly at both transcript and protein level." (PMID 35874683, 2022).
vitiligo (1 paper, 2018). Generalized well circumscribed patches of leukoderma that are generally distributed over symmetric body locations and is due to autoimmune destruction of melanocytes. "From the studied cytokine receptors, only IL22RA1 (p < 0.05) expression was increased in the non-lesional skin of vitiligo patients compared with the skin of control subjects." (PMID 30515176, 2018).
tumor (36 papers, 2010 to 2025). "Immune cell infiltration level in tumor tissues is associated with IL22RA1 expression." (PMID 35874683, 2022). "The targeted depletion of IL-22RA1 from IECs leads to the suppression of apoptosis triggered by DNA damage, consequently leading to increased tumor formation in an inflammation-driven tumor model." (PMID 39379604, 2024). "We further performed correlation analysis between IL22RA1 and tumor infiltrating immune cells in different types of cancer, as IL22 is produced mainly by immune cells." (PMID 35874683, 2022). "Taken together, our analysis indicates that IL22RA1 contributes to tumor progression through activating the JAK/STAT signaling pathway." (PMID 35874683, 2022). "Consistent with IL22RA1, higher expression of IL10RB, IL10RA and IL20RB in tumor tissues was associated with worse survival in patients." (PMID 35874683, 2022). "Taken together, IL-22 exerts its tumor-promoting effects mainly via IL-22RA1-mediated signaling on hepatocytes." (PMID 36551508, 2022). "Although the IL(R)-based signature exhibited powerful predictive ability, these signature members themselves (IL-7R, IL-5RA, IL-20RB, IL-11, and IL-22RA1) were rarely reported to be used to predict tumor prognosis." (PMID 34497605, 2021). "In our results, IL‐22RA1 expression continuously increased with the tumor progression whereas the expression of IL‐22BP only increased during the cell proliferation stages and declined as the cancer progressed to the invasion stage." (PMID 31725949, 2020). "Notably, increased IL-22RA1 gene copy number and mRNA expression have been observed in primary tumor tissues, suggesting a potential for heightened IL-22 responsiveness in tumor cells." (PMID 40806452, 2025). "The mRNA expression level of IL22RA1 was highest in the pancreas among tumor tissues." (PMID 35874683, 2022). "In contrast to IL‐22RA1, IL‐22BP mRNA expression only increased during the initiation and hyperplasia stages (4–8 weeks) and decreased significantly from the early carcinoma stage to the late carcinoma stage (8–14 weeks) of tumor development." (PMID 31725949, 2020). "A total of 30 IL22RA1-correlated genes (e.g. IL17D, IL22RA2, IL20RB, IL10RA, IL10RB, TSLP and TYK2) are involved in the JAK/STAT pathway which promotes tumor progression." (PMID 35874683, 2022). "The results showed that GPI, IL22RA1, CCT6A, and SPOCK1 expression in the tumor tissues (T) was markedly higher than in the control tissues (N) (n=40, P<0.05)." (PMID 35433415, 2022). "IL22RA1 is an important heterodimeric receptor for interleukin 22 (IL22) which is involved in chronic inflammation and tumor development." (PMID 35874683, 2022). "A recent report showed that colonic IL-22RA1-KO impairs apoptosis and gene inductions related to DNA repair in response to DSS and azoxymethane treatment and promotes subsequent tumor development." (PMID 34759916, 2021). "In the viral cytokine receptor pathway, upregulated genes (p = 1.39 × 10−5), including TNFRSF1A, CCL21, IL2RB, IL22RA1, and XCR1, suggest that oncolytic viruses exploit tumor-specific immune evasion mechanisms to selectively lyse tumor cells, activating anti-tumor immunity via DAMPs and PAMPs." (PMID 40406701, 2025). "Additionally, older patients with a tumor exhibited elevated FUT2, FUT3, and FUT8 coexpression with tumor-promoting IL6ST, IL22RA1, TGFB1, and TGFBR1 genes compared with young tumor." (PMID 38456503, 2024). "However, the relationship between IL22RA1 and various types of IL22-producing cells in specific tumor tissues still needs to be confirmed in the future." (PMID 35874683, 2022). "Interestingly, we found their receptors, IL17RA/IL17RC for IL17A/IL17F, IL10RB/IL22RA1 for IL22, and IL20RA/IL10RB for IL26, were upregulated in tumor cell than in normal epithelial cells." (PMID 35999201, 2022).
tumor (continued). "IL22RA1 is a receptor of interleukin 22, has been reported working as a signal transducer and activator of STAT3 signaling in the malignant transformation, it plays an important role in promoting tumor growth and metastasis and inhibiting cell apoptosis." (PMID 34040139, 2021).
cancer (19 papers, 2011 to 2025). A tumor composed of atypical neoplastic, often pleomorphic cells that invade other tissues. "CCND1 is dysregulated in many cancers, indicating mutation of IL22RA1 contributes to cancer development." (PMID 35874683, 2022). "High expression of IL‐22RA1 in cancer cells is associated with poor prognosis in pancreatic ductal carcinoma (DC) patients." (PMID 31725949, 2020). "We further explored the correlation of IL22RA1 and the related 30 genes in each cancer (from TIMER2)." (PMID 35874683, 2022). "In conclusion, IL22RA1 together with genes involved in the JAK/STAT pathway contribute to cancer development." (PMID 35874683, 2022). "Given that common and specific roles of cytokines/receptors in multiple cancers, we conducted a pan-cancer study to investigate the role of IL22RA1 in cancer using The Cancer Genome Atlas (TCGA) database." (PMID 35874683, 2022). "As expected, the upregulated expression of IL22RA1 in 11 cancers was correlated with different immune cell infiltrates." (PMID 35874683, 2022). "We then used TIMER2.0 to evaluate the correlation between IL22RA1 expression and infiltration level of immune cells estimated by all six algorithms across TCGA cancer types." (PMID 35874683, 2022). "In this study, we demonstrated the role of receptor of IL22 (IL22RA1) in cancers by studying the crosstalk between IL22RA1 and immune system." (PMID 35874683, 2022). "Our study shows that correlation between IL22RA1 expression and different immune cells infiltration depends on the type of cancer." (PMID 35874683, 2022). "Correlation between IL22RA1 and immune cells in cancers with significance." (PMID 35874683, 2022). "Notably, we found IL22RA1 transcript was upregulated in 11 cancer types compared with their corresponding control." (PMID 35874683, 2022). "Our study used the TCGA databases to conduct a pan-cancer analysis of IL22RA1 for the first time." (PMID 35874683, 2022). "The correlation between IL22RA1 expression and immune cell infiltration depends on cancer type." (PMID 35874683, 2022). "Our study suggests that IL22RA1/JAK/STAT signaling can be an important target for cancer treatment." (PMID 35874683, 2022). "As a mediator of immune cell-epithelial cell crosstalk, the association of IL22RA1 and immune cell infiltration in cancer is not clear." (PMID 35874683, 2022). "Since IL22RA1 is especially expressed on barrier surfaces, low expression levels could be due to replacement of the physiological esophageal mucosa by cancer cells." (PMID 32100077, 2020). "In cancer, the role of IL‐22/IL‐22RA1 axis is complex and context‐dependent." (PMID 31725949, 2020). "For example, IL-20RA and IL-22RA1 expression is confined to specific tissues and is essentially absent from hematopoietic lineages; thus, the selective distribution underscores the specialized roles of these cytokines in tissue homeostasis and in several diseases, including cancer." (PMID 40806452, 2025). "IL22RA1 was positively correlated with STAT1, STAT3, JAK1, PTPN11, IFNA13, IL24, but negatively correlated with IL10 in specific cancers." (PMID 35874683, 2022). "Importantly, IL-22 was found to enhance PC stemness through IL-22RA1/STAT3 signaling, elucidating the role of microenvironmental factors in regulating cancer stemness." (PMID 40806452, 2025). "It is worth to note that the non-silent mutation rate of IL22RA1 is high in UCEC and SKCM compared with the other types of cancer." (PMID 35874683, 2022). "Expression of other receptor molecules (IL13RA1, IL15RA, IL22RA1 and IFNGR1/2) was increased in carcinoma tissue, however due to our FC restriction we did not test these mRNAs for associations with miRNA differential expression." (PMID 30603058, 2018).
infection (16 papers, 2014 to 2025). The state of being infected such as from the introduction of a foreign agent such as serum, vaccine, antigenic substance or organism. "Following infection, expression of IL-22Ra1 is highly increased in injured areas of the distal lung." (PMID 32582219, 2020). "During infections, neutrophil serine proteases also can degrade IL-22Ra1 providing another mechanism of control of IL-22 signaling." (PMID 32582219, 2020). "Focused use of floxed IL-22Ra1 mice should enable high resolution study of tissue and cellular compartments where IL-22 signaling is required during infection." (PMID 32582219, 2020). "Given the potential of IL-22 to restore the pulmonary barrier and restore lung function after infection, we believe it is important to understand the cells upon which IL-22 will act and mechanisms in which the IL-22Ra1 produced." (PMID 31416461, 2019). "While research has been focused on the cytokine itself, there is limited understanding of the regulation of the IL-22 receptor (IL-22Ra1) at the epithelial surface during infection." (PMID 31416461, 2019). "Moreover, upregulation of IL-22Ra1 may be an important mechanism to promote epithelial repair by allowing IL-22 to signal to cells that are undergoing infection, stress or injury." (PMID 31416461, 2019).
inflammation (2 papers, 2021 to 2024). Aberrant reaction of the microcirculation characterized by movement of fluid and leukocytes from the blood into extravascular tissues. "Previous study first reported that IL-22RA1 is expressed on the lung epithelial cells in OVA-induced airway inflammation." (PMID 34836520, 2021). "To explore the potential mechanisms of IL-22 which inhibited the OVA-induced airway inflammation, we performed immunohistochemistry to detect the expression of functional IL-22 receptor, a heterodimer of IL-22RA1 and IL-10RB, and its soluble binding protein, IL-22BP." (PMID 34836520, 2021).
bacterial infection (1 paper, 2023). "Recently, Paneth cells were found to express IL-22 receptor, IL-22RA1, and mice with Paneth cell-specific Il22ra1 deficiency were susceptible to bacterial infection." (PMID 37908362, 2023).
metabolic disorders (1 paper, 2024). "In this study, we elucidate the tissue-specific role of IL-22RA1 signaling in mediating the onset of HFD-driven metabolic disorders." (PMID 38383607, 2024). "Here we examine the importance of tissue-specific IL-22RA1 signaling in mediating long-term high fat diet (HFD) driven metabolic disorders." (PMID 38383607, 2024).
IL22RA1 also shares sentences with these, for which no sentence is quoted: breast carcinoma (7 papers); anaplastic large cell lymphoma (3); rheumatoid arthritis (3); ulcerative colitis (3); asthma (2); atopic dermatitis (2); colorectal cancer (2); dermatitis (2); Erythema (2); fatty liver (2); graft versus host disease (2); Hyperglycemia (2); inflammatory bowel disease (2); lupus nephritis (2); myocarditis (2); primary Sjogren syndrome (2); steatosis (2); alcohol-induced acute pancreatitis (1); alcoholic liver diseases (1); autoimmune uveitis (1); Autoimmunity (1); B cell lymphoma (1); bladder urothelial carcinoma (1); Breast Tumors (1); cardiovascular diseases (1); cervical (1); cholangiocarcinoma (1); cholangitis (1); Chronic colitis (1); chronic pancreatitis (1).
A further 51 diseases each share a sentence with IL22RA1 in 1 paper.